BRAF (B-Raf proto-oncogene, serine/threonine kinase)
Diseases named in the same sentence as BRAF in open-access papers (continued):
Sharing a sentence is not in itself a finding about the gene and the disease.
skin cancer (continued). "Activation of c-Raf caused by BRAF inhibitors in tumors with activated Ras has been shown, paradoxically, to stimulate, rather than inhibit MAPK pathway signaling and is suspected of causing new skin cancers that have been observed as a frequent side effect of BRAF inhibitors." (PMID 25520658, 2014). "For example, several associations with BRAF(A) did not validate in the Score dataset; this is not surprising since the majority of BRAF(A) mutations in the Avana dataset are in the 54 skin cancer cell lines, while the Score dataset contains only 4 skin cancer cell lines." (PMID 35382456, 2022). "Here, also, we found that skin cancer cell lines were significantly more dependent on MAPK1 (t = 16.5, p = 1.33 × 10−55) and BRAF (t = 17.9, p = 1.6 × 10−63) expression than were other cell lines." (PMID 33398072, 2021). "Herein, we investigated the impact of BRAF inhibition on Mus musculus papillomavirus 1 (MmuPV1)-induced skin tumor development in non-tg, naturally infectable mice to overcome the inherent limitations associated with tg expression of the viral genes." (PMID 39335105, 2024). "In summary, this study provides experimental evidence that inhibition of BRAF and UVB light act synergistically in favoring papillomavirus-infection-induced skin tumor development in vivo, and it reveals a novel pathway additional to the paradoxical activation of MAPK signaling." (PMID 39335105, 2024). "Pathophysiologically, BRAF-inhibitors can bind to and activate wild-type RAF leading to “paradoxical” MAPK-pathway activation in BRAFV600 wild-type skin cells, which manifests clinically as skin neoplasms." (PMID 33921947, 2021). "A search on that matter has led us to understand that no study in our region was conducted on the prevalence of BRAF V600E expression in skin cancers." (PMID 31531096, 2019). "In this context, v-Raf murine sarcoma viral oncogene homolog B (BRAF) inhibitor, dabrafenib therapy has triggered rapidly-growing skin tumors, which can be partially mitigated by combination with trametinib, a mitogen-activated protein kinase kinase (MEK) inhibitor." (PMID 31480389, 2019). "In particular, it is conceivable that BRAF inhibition in conjunction with UVB irradiation may utilize properties of the papillomavirus to contribute to skin tumorigenesis and, possibly, ultimately to skin cancer." (PMID 39335105, 2024). "Similarly to recurrent BRAF mutations, non-canonical C>T, C>A, T>A, and T>C mutations in NRAS are 2.6- to 38-fold enriched within skin cancers compared with non-skin cancers." (PMID 33207206, 2020). "When each indication was classified further according to BRAF, RAS mutation status, or wild-type (no RAF or RAS mutations), the strength of the correlations appeared to diminish, though still significant, with skin cancer remaining the most sensitive indication to cobimetinib treatment." (PMID 29872725, 2018). "In contrast, in the absence of one component, namely systemic BRAF inhibition or UVB light, significantly fewer virus-induced skin tumors were observed." (PMID 39335105, 2024). "Similarly, K14-HPV38-E6/E7 tg mice, which express the beta-HPV38 E6 and E7 oncogenes in the basal layer of the epidermis, consistently developed large cSCCs after exposure to BRAF inhibition and UVB light irradiation, whereas equally treated WT controls failed to develop skin tumors." (PMID 39335105, 2024).
hairy cell leukemia (93 papers, 2013 to 2026). Hairy cell leukemia (HCL) is a rare type of leukemia in which abnormal B-lymphocytes are present in the bone marrow, spleen and peripheral blood. "BRAF mutations are associated with a small number of hematologic malignancies, including hairy cell leukemia and histiocytic disorders." (PMID 38406519, 2024). "In hairy cell leukemia the BRAF Val600Glu (V600E) mutation is found in nearly all cases at diagnosis and considered as the causal genetic event." (PMID 36275468, 2022). "In B-cell neoplasms, BRAF V600E mutations are highly sensitive for hairy cell leukemia (HCL), seen in essentially 100% of cases." (PMID 33801781, 2021). "In hematological malignancies, BRAF mutations occur in approximately 7% of multiple myeloma and almost 100% of classical hairy cell leukemias (HCL)." (PMID 33042833, 2020). "Hairy cell leukemia (HCL) is a purine analog-responsive B-cell malignancy containing the BRAF V600E mutation, expressing CD22, CD11c, CD103, tartrate resistant acid phosphatase (TRAP) CD25, CD123, and annexin 1A." (PMID 32040482, 2020). "BRAF V600E mutation has been reported in de novo HS and HS following splenic marginal zone lymphoma and hairy cell leukemia." (PMID 29463311, 2018). "More recently, a V600E BRAF mutation in hairy cell leukemia, an L265P MYD mutation in Waldenström macrogloblinemia, and several mutations in STAT3 in large granular lymphocytic leukemia have been identified as diagnostics of these tumor types." (PMID 25310466, 2014). "Since the initial report of the BRAF V600E mutation in hairy cell leukemia, numerous investigators have demonstrated the presence of this activating mutation in nearly all cases of this disease." (PMID 23653869, 2013). "Furthermore, Gene Set Enrichment Analysis (GSEA) confirmed that BRAFV600E induced the activation of pathways associated with AP-1, MAPK and a BRAF mutant signature like hairy cell leukemia." (PMID 39617757, 2024). "Hairy cell leukemia (HCL) is a B-lymphoma induced by BRAF(V600E) mutation." (PMID 37543582, 2023). "BRAF V600E mutations are present in almost all cases of hairy cell leukemia (HCL) at diagnosis." (PMID 35627184, 2022). "Splenic pathology confirmed hairy cell leukemia with a BRAF mutation." (PMID 36051021, 2022). "Splenic pathology confirmed the diagnosis of hairy cell leukemia (positive BRAF mutation)." (PMID 36051021, 2022). "However, these thresholds can be reduced for specific variants that need to be detected at low frequencies (e.g., BRAF c.1799T>A; p.(Val600Glu) in hairy cell leukaemia) but an extensive validation is needed here as well." (PMID 31888289, 2019). "Hairy cell leukemia (HCL) is caused by the kinase‐activating BRAF‐V600E mutation in > 95% of patients, making this disease sensitive to oral BRAF inhibitors." (PMID 40847803, 2026). "In hematologic malignancies, BRAF mutations have been frequently identified in hairy cell leukemia (HCL), Erdheim–Chester disease, Langerhans cell histiocytosis, and plasma cell neoplasms." (PMID 38791222, 2024). "The BRAF V600E mutation interests 70–100% of hairy cell leukemias (HCL) patients, but also up to 50% of cases of Langerhans cell histiocytosis, especially those with skin or central nervous system involvement." (PMID 35741115, 2022). "Hairy cell leukemia (HCL) is an indolent B-cell neoplasm with “hairy cells” in the peripheral blood and bone marrow aspirates, and characteristic BRAF V600E mutation." (PMID 27600067, 2015). "We report a case of an otherwise asymptomatic patient who was initially investigated for CRC, through plasma-only analysis of ctDNA a BRAF mutation was detected, and subsequent MTB discussion led to the diagnosis of hairy cell leukaemia." (PMID 39516362, 2024). "Typically, all patients with hairy cell leukemia (HCL) harbor variants in the BRAF gene." (PMID 35893795, 2022).
hairy cell leukemia (continued). "Nevertheless, BRAF plays an important role in some B cell neoplasms as virtually 100% of typical hairy cell leukemia and about 1 to 5% of chronic lymphocytic leukemia and myeloma contain BRAF mutations." (PMID 35965494, 2022). "Hairy cell leukemia (HCL), which commonly carries the BRAF V600E mutation, was distinctly responsive to BRAF and MEK inhibition." (PMID 29227286, 2018). "Except for cyclin D1 and BRAF, the immunophenotype was similar to that of hairy cell leukaemia." (PMID 40282427, 2025). "The absence of MYD88 excluded lymphoplasmacytic lymphoma, and the absence of a BRAF mutation excluded hairy cell leukemia." (PMID 41531558, 2025). "Nevertheless, some cancers, such as hairy cell leukemia, almost exclusively express BRAF V600E mutations with few to no other known oncogenic drivers." (PMID 35565240, 2022). "Similarly, detection of a BRAF V600E in hairy cell leukaemia often requires a VAF below the general threshold of the panel." (PMID 31888289, 2019). "Activating mutations in BRAF were found in CLL (N = 3 of 39 patients; two with BRAF G469A and one with BRAF V600E), multiple myeloma (N = 1 of 17; BRAF V600E), hairy cell leukemia (HCL) (N = 1 of 1; BRAF V600E) and Erdheim Chester disease (ECD) (N = 1 of 1 patient; BRAF V600E)." (PMID 30583461, 2018). "Hairy cell leukemia was ruled out due to the lack of CD11c and negative BRAF mutation testing." (PMID 40271287, 2025). "A similar mutual exclusivity of BRAF and MAP2K1 mutations has also been reported in other neoplasms, including hairy cell leukemia (HCL) and various epithelial malignancies." (PMID 32483240, 2020). "In order to exclude lymph node involvement by hairy cell leukemia (HCL), all BRAF mutant NMZL were carefully reevaluted and stained for CD103 and Annexin A1 and turned out to be negative; in addition, all of them were negative for cyclin D1." (PMID 29556019, 2018). "BRAF V600E mutations are common in solid tumors, including melanoma and papillary thyroid cancer, and hematologic neoplasms, such as Langerhans cell histiocytosis (LCH) and hairy cell leukemia (HCL), but infrequent in myeloid malignancies." (PMID 39596583, 2024). "Activating mutations in BRAF have been described in MM ( ̃50%), thyroid (THCA, 30–50%), colorectal (CRC, 10%), non-small cell lung (NSCLC, 3%) cancers and in hairy cell leukemia (HCL, 100%)." (PMID 35272691, 2022). "Unlike classical hairy cell leukemia (HCL-c), HCL-v typically lacks the BRAF V600E mutation, thereby limiting the use of BRAF inhibitors and complicating treatment strategies." (PMID 40900797, 2025). "Here we report on a patient with BRAF mutant hairy cell leukemia and monoclonal B-cell lymphocytosis (MBL), who responded durably to BRAF/MEK inhibitors (BRAFi/MEKi) but experienced transformation of a RAS mutant MBL to chronic lymphocytic leukemia (CLL) with accelerated nodal progression." (PMID 33042833, 2020).
thyroid (90 papers, 2009 to 2026). "The BRAF V600E mutation is a key molecular marker for malignancy in thyroid nodules showing cytological features of atypia of undetermined significance (AUS)." (PMID 40970023, 2025). "This prospective study demonstrated that the ThyroSCAN PanelChip effectively identified BRAF V600E mutations in thyroid nodules using FNA residual thyrocytes." (PMID 40310607, 2025). "One of the most described genetic alterations leading to thyroid carcinogenesis is the BRAF V600E point mutation." (PMID 38203733, 2024). "The study aims to describe the frequency and clinicopathologic characteristics of BRAF non-V600E mutations in a large cohort (1654 samples) of thyroid lesions characterized by next-generation sequencing." (PMID 36835466, 2023). "Many investigators have reported that detection of RET/PTC, TRK and BRAF(V600E) in FNAB specimens is proposed as a diagnostic adjunctive tool in the evaluation of thyroid nodules with suspicious cytological findings." (PMID 27348515, 2016). "Incidence of concurrent cancer, underlying thyroiditis and positive BRAF mutation were significantly higher in 142 nodules with direct surgery than 243 nodules with repeat FNA (p < 0.05)." (PMID 26115096, 2015). "When comparing clinicopathologic and US features between the direct surgery group and the repeat FNA group, incidence of concurrent cancer, underlying thyroiditis and positive BRAF mutation were significantly higher in direct surgery group (p < 0.05)." (PMID 26115096, 2015). "This study is one of the first comprehensive surveys on BRAF mutations in different types of thyroid diseases carried out so far in the MENA region." (PMID 22925390, 2012). "In addition, compared to US-FNAB, combined US-FNAB with BRAF V600E mutation has obviously superior PTC differentiating ability for macro-calcified thyroid nodules, especially with a significantly higher sensitivity." (PMID 37194091, 2023). "Droplet digital PCR (ddPCR) has been reported to have a superior validity over PCR with amplification‐refractory mutation system (ARMS‐PCR) for detecting the BRAF V600E mutation in thyroid nodule fine‐needle aspiration (FNA) samples using cytological diagnosis as the reference." (PMID 32671901, 2020). "miR-146b-5p positively regulates migration and invasion of thyroid normal and tumor follicular cells (independently from their original mutation, either BRAF or RET/PTC), through a mechanism that involves the actin cytoskeleton but not an increased capacity of matrix degradation." (PMID 26883911, 2016). "However, direct surgery group also had higher probability of concurrent cancer, positive BRAF mutation and underlying thyroiditis (p < 0.05)." (PMID 26115096, 2015). "Like the MAP kinase pathway aberrantly activated by the BRAF mutation that plays a fundamental role in thyroid tumorigenesis, particularly in PTC, aberrantly activated RAS/PI3K/AKT pathway (PI3K pathway) is another fundamental mechanism in thyroid tumorigenesis, particularly in FTC and ATC." (PMID 26472282, 2015). "The BRAF V600E mutation is found in more than 50% of all thyroid malignancies (primarily PTC)." (PMID 29147373, 2014). "This study aimed to verify the prevalence of mutations in the BRAF, and RAS genes, and RET/PTC rearrangements in patients undergoing fine-needle aspiration biopsy (FNAB) for thyroid nodule evaluation in a real-world public health service population." (PMID 40748901, 2025). "As our multivariate analysis revealed, only a subset of genes—specifically TERT and BRAF—along with clinical factors (T stage and unilateral thyroid involvement) were independently predictive of lung metastasis." (PMID 41306438, 2025). "Previous research has identified similar methylation patterns, particularly in genes such as BRAF, which is known to be involved in thyroid carcinogenesis through activation of the MAPK signaling pathway." (PMID 40450370, 2025).
thyroid (continued). "A higher proportion of patients with thyroiditis had previously received BRAF/MEK inhibition (58% versus 31%, p = 0.003)." (PMID 38136348, 2023). "The relationship between BRAF V600E AF and the histopathological features of thyroid malignancies is not well understood." (PMID 38201541, 2023). "Our finding of a higher proportion of thyroiditis in patients who previously received BRAF/MEK inhibition (58% versus 31%, p = 0.003) has to our knowledge not been previously reported." (PMID 38136348, 2023). "Both BRAF and RAS mutations can promote thyroid tumorigenesis, but endow the cells with different characteristics." (PMID 36056964, 2022). "Because of the active roles of BRAF-mediated signaling in thyroid carcinogenesis, the status of the BRAF gene in the three ATC cell lines employed in the current study was investigated." (PMID 36430869, 2022). "E26 transformation-specific (ETS) factors have been regarded as the principal end-effectors of the BRAF-ERK signaling cascade, implicated in thyroid carcinogenesis." (PMID 34281460, 2021). "BRAF mutation has low prevalence in the FN/SFN and AUS/FLUS while high in the SM cytology thyroid lesions." (PMID 31531363, 2019). "We also showed that BRAFT1799A-induced thyroid oncogenesis model in vivo (Tg-BRAF transgenic mice) increased FAM83F expression in 5-week-old PTC mice, altogether indicating a cross regulation of FAM83F and MAPK signaling." (PMID 30881348, 2019). "At the time of last follow up, five patients died of thyroid disease: four in the TERT+BRAF mutation group and one in the BRAF mutation alone group." (PMID 29312581, 2017). "The ERK-regulated ETS factor ELK1 was a candidate of particular interest, given the importance of BRAF-ERK signalling as a driver of thyroid tumorigenesis." (PMID 27852061, 2016). "The objective of the study was to determine if the analysis of mutations (BRAF, NRAS, KRAS and HRAS) using readily available molecular techniques can help better classify indeterminate thyroid nodules." (PMID 26621130, 2015). "This mutation occurs in the majority of cases and results in the constitutively activated BRAF kinase, which plays a fundamental role in thyroid tumorigenesis through driving Ras/Raf/MEK/ERK (MAPK) signaling pathway." (PMID 24588959, 2014). "Our study demonstrates STRA6 may serve as a prognostic marker for BRAF-mutated PTC, which may drive thyroid carcinogenesis via activation of oncogenic pathway and regulation of tumor immunosuppressive microenvironment." (PMID 36843593, 2023). "We assessed the impact of BRAF mutations in cancerous and non-cancerous thyroid lesions originating in an ethnically diverse population by a comprehensive mutational survey." (PMID 22925390, 2012). "However, the isolated presence of BRAF V600E mutation is unlikely to discover the full picture of thyroid carcinogenesis due to its poor sensitivity." (PMID 39568807, 2024). "Our analysis, however, highlights substantial differences in DNAm between BRAF-mutated vs. NRAS- and HRAS-mutated THCA tumors; moreover, the differences in DNAm appear to profoundly shape gene expression profiles, which may contribute to thyroid tumorigenesis." (PMID 29125844, 2017). "Regarding the selected genes in other CNA/UPD areas, the AKT3/PIK3CA pathway, the KRAS/RAP1B/RAP1GAP/BRAF pathway, and the VEGFC pathway have been known to participate in thyroid carcinogenesis/cancer progression." (PMID 22558328, 2012). "While the BRAF V600E mutation is commonly linked to PTC, its presence does not exclude other types of thyroid malignancies." (PMID 39288226, 2024).
thyroid (continued). "Although the single mutational testing for BRAFV600E has high specificity for thyroid malignancy, the 2015 ATA guidelines do not recommended the systematic use of the single molecular status of BRAF; and a mutational panels (RAS, BRAF, RET/PTC.)." (PMID 34394248, 2020). "BRAF mRNA expression was higher in patients < 45 years and in those without thyroiditis, with a tumor size > 2.0cm, and with N1 nodal stage." (PMID 27410688, 2016). "As expected, PTCs exhibited much lower TDS than asymptomatic thyroids, while the differences between the BRAF(+) and (-) normal/benign thyroids were much smaller and non-significant." (PMID 26625260, 2015). "After comparison of non-malignant BRAF(+) thyroids to BRAF(−) ones, we selected 862 significantly deregulated genes." (PMID 26625260, 2015). "However, it was not correlated with gender distribution, tumor size, thyroiditis, thyroid-stimulating hormone (TSH) level, and BRAF mutation." (PMID 40143394, 2025). "Indeed, the oncogenic activation of BRAF leads to constitutive activation of downstream signaling through MAPK pathway and favors the development of biologically and clinically aggressive thyroid and colorectal malignancies, frequently resistant to conventional anticancer therapies." (PMID 29033690, 2017). "None of the factors, including age, gender, thyroiditis, ETE, tumor size, AJCC stage, recurrence, or vital status, differed significantly between the BRAFV600E and wild-type BRAF patients." (PMID 27410688, 2016).